LINC00161 (long independently transcribed non-coding RNA 161)
Synonyms: HORAS5; C21orf100; Linc-USP16; NCRNA00161
Gene: Long non-coding RNA gene on chromosome 21 (28,539,318 to 28,543,283, forward strand). Ensembl gene ENSG00000226935.
Diseases named in the same sentence as LINC00161 in open-access papers:
LINC00161 is named in the same sentence as 7 diseases in open-access papers, as found by Europe PMC text mining. Sharing a sentence is not in itself a finding about the gene and the disease. The quoted sentences say what the papers report.
hepatocellular carcinoma (4 papers, 2017 to 2023). A malignant tumor that arises from hepatocytes. "LINC00161 is an oncogene that is involved in promoting the migration and invasion of hepatocellular carcinoma (HCC)." (PMID 37546394, 2023). "Aberrant expression of LINC00161 has been reported in some cancer types, however, the association of LINC00161 and hepatocellular carcinoma (HCC) has not been evaluated." (PMID 28915581, 2017). "Expressions of LINC00161/Linc-USP16 in exosomes derived from hepatocellular carcinoma (HCC) patient serum and HCC cell line supernatants were significantly associated with angiogenesis, metastasis, and poor survival." (PMID 37456253, 2023).
osteosarcoma (2 papers, 2017 to 2019). A usually aggressive malignant bone-forming mesenchymal neoplasm, predominantly affecting adolescents and young adults. "Dysregulation of LINC00161 has been documented to play an important function in osteosarcoma." (PMID 28915581, 2017).
LINC00161 also shares sentences with these, for which no sentence is quoted: cancer (2 papers); Down syndrome (1); liver cancer (1); prostate carcinoma (1); tumor (1).